EIF4G1 (eukaryotic translation initiation factor 4 gamma 1)
Diseases named in the same sentence as EIF4G1 in open-access papers (continued):
Sharing a sentence is not in itself a finding about the gene and the disease.
tumor (continued). "EIF4G1 was found to be more significantly upregulated in the tumor tissues than in the paired adjacent normal tissues, in both the TCGA cohort (p < 2.2 × 10–16) and the GSE42568 cohort (p = 8.1 × 10–5)." (PMID 36551184, 2022). "EIF4G1 is required for cap-dependent mRNA translation which is a necessary process for tumor growth and survival." (PMID 35787690, 2022). "In conclusion, our results suggest that activation of mTOR signalling is required for EIF4G1‐induced tumour growth in NSCLC." (PMID 33523588, 2021). "We confirmed high levels of EIF4G1 expression in the cytoplasm of NSCLC tumour cells and much lower EIF4G1 expression in the adjacent normal lung tissues from most patients." (PMID 33523588, 2021). "Immunohistochemical staining confirmed that the tumours from the EIF4G1 knockdown cell‐injected mice had much lower EIF4G1 protein expression." (PMID 33523588, 2021). "Analysis of the samples obtained showed a reduction in eIF4E:eIF4G1 interaction among tumours treated with SBI-756 as a single agent or in combination with venetoclax, compared to vehicle or venetoclax alone." (PMID 33318657, 2021). "We found that EIF4G1 knockdown A549 cells dramatically inhibited NSCLC tumour growth in mice compared to control cells." (PMID 33523588, 2021). "Taken together, these data indicate again the potential immunoregulatory function of EIF4G1 network in NSCLC tumour cells." (PMID 33539648, 2021). "Some studies have shown that the eukaryotic translation initiation factor EIF4G1 plays a positive role in the processes of tumour formation, proliferation and metastasis." (PMID 33523588, 2021). "NSCLC tissue arrays, which contain normal lung tissues (n = 10), tumour and paired adjacent tissues from the same patients (n = 45), were used to measure EIF4G1 expression through immunohistochemistry." (PMID 33539648, 2021). "In contrast, these compounds show much less inhibitory effects on normal lung cells in the same doses range, because of the significant elevation of EIF4G1 and related protein levels in tumour cells." (PMID 33539648, 2021). "Tumour suppressor PDCD4 competes with EIF4A for binding to EIF4G1, as such inhibiting the initialization of translation." (PMID 33523588, 2021). "We identified the effects of EIF4G1 on tumour cell growth and in vivo tumorigenesis, confirmed the increased expression levels of EIF4G1 in primary NSCLC tissues, and observed a positive correlation between the levels of EIF4G1 and the progression of NSCLC." (PMID 33523588, 2021). "In hypoxic tumor cells, HIF-1 up-regulated eIF4E1, resulting in the enhanced translation of certain mRNAs encoding proteins, such as c-Myc, Cyclin-D1, and eIF4G1, which are important for BC cell three-dimensional structure growth." (PMID 32708122, 2020). "Overall, data showed that increased EIF4G1 levels in tumor tissues result from amplification and or mRNA up-regulation." (PMID 31496918, 2019). "eIF4G1, a critical component of the eIF4F complex, is required for cap-dependent mRNA translation, a process necessary for tumor growth and survival." (PMID 29748619, 2018). "Analysis of the TCGA data revealed that eIF4G1 gene expression positively correlated with higher tumor grade and stage." (PMID 29748619, 2018). "Our result showed that mRNA level of eIF4G1 in primary tumor was significantly higher compared to normal prostate tissue (p = 1.62E-12)." (PMID 29748619, 2018). "Here we report for the first time, the expression of eIF4G1 is significantly increased in PCa cell lines and tumor tissues and in multiple clinical cohorts as compared to respective controls." (PMID 29748619, 2018). "The eIF4G1 expression was significantly correlated with the clinical tumor stage (P = 0.0004) and omentum metastasis (P = 0.024)." (PMID 27668427, 2016). "Silencing of EIF4G1 dramatically reduced its expression when compared to the control cells in these tumor cells." (PMID 27003362, 2016).
tumor (continued). "We further examined the effect of EIF4G1 on the expression of PDCD4, a key tumor suppressor protein interacting with EIF4G1 and controlling tumor growth and invasion." (PMID 20398343, 2010). "This complex is regulated by the 4EBP1, a translational repressor that inhibits the function of eukaryotic translation initiation factor 4E (EIF4E), which compete with EIF4G1 for binding to eIF4E and have tumor-suppressor activity." (PMID 20398343, 2010). "In addition, we found that EIF4G1 exerts a pro-inflammatory effect by modulating CXCL8 to affect the chemotaxis of macrophages toward tumor cells, a view supported by a previous report on CXCL8." (PMID 38405671, 2024). "EIF4G1 was found to be more expressed in tumor tissues than para-cancerous breast tissues." (PMID 36551184, 2022). "The relationship between EIF4G1 and tumor microenvironment (TME) was analyzed." (PMID 36551184, 2022). "The inhibition of mTOR attenuated the EIF4G1‐induced development and progression of tumours." (PMID 33523588, 2021). "In addition to promoting protein translation, EIF4G1 plays an important role in the initial stage of eukaryotic cell translation and is closely related to the occurrence and development of tumours." (PMID 33523588, 2021). "Subsequently, targeted knockdown of EIF4G1 inhibited xenograft tumour growth in vivo." (PMID 33523588, 2021). "Furthermore, EIF4G1 was potentially required for NSCLC metastasis through promoting tumour cell migration and invasion." (PMID 33539648, 2021). "In conclusion, the current study indicated that upregulation of EIF4G1 could activate the mTOR signalling pathway, thereby promote the tumour progression in NSCLC." (PMID 33523588, 2021). "Our results suggest that eIF4G1 expression may help stratify PCa patients and may serve as a tumor marker for distinguishing indolent disease from lethal PCa." (PMID 29748619, 2018). "Furthermore, we found that EIF4G1 expression was significantly up-regulated in most NSCLC tumor tissues we detected (13/18, 72%) when compared to the respective adjacent normal lung tissue from the same patients." (PMID 27003362, 2016). "In addition to examining the biological functions of EIF4G1 in vitro, we also assessed the in vivo function of EIF4G1 in a xenograft tumor transplantation model." (PMID 20398343, 2010). "In addition, the levels of EIF4G1 protein in tumors were positively correlated with tumor T classification (P = 0.039), lymph node involvement (N classification, P = 0.008), and the clinical stages (P = 0.003) of NPC patients." (PMID 20398343, 2010). "Using shRNA to knock down the expression of EIF4G1 not only markedly inhibited cell cycle progression, proliferation, migration, invasion, and colony formation, but also dramatically suppressed in vivo xenograft tumor growth." (PMID 20398343, 2010). "Besides, increased EIF4G1 could promote the formation of tumor emboli by facilitating the translation of IRES-containing p120 mRNAs." (PMID 36551184, 2022). "Moreover we observed a graded increase in eIF4G1 mRNA expression with increasing tumor grade (Gleason Score) with a significant p-value with the comparison between normal to Gleason Score (GS) 6 (p = 1.56E-05), GS 7 (p = 1.62E-12), GS 8 (p = 6.52E-13), GS 9 (p < 1E-12) and GS 10 (p = 2.83E-04)." (PMID 29748619, 2018). "In addition, studies have demonstrated that eIF4G1 promotes phenotypic responses that may assist tumor cells to develop drug resistance." (PMID 27668427, 2016). "HPA indicated that the protein level of EIF4G1 was higher in normal breast tissues and BRCA samples than in normal organs and tumor tissues." (PMID 36551184, 2022). "The correlation between tumor microenvironment (TME) and EIF4G1 was performed via ESTIMATE, CIBERSORT algorithms, and GEPIA." (PMID 36551184, 2022). "Taken together, our results suggest that EIF4G1 is closely related to the occurrence and development of NSCLC tumours." (PMID 33523588, 2021).
tumor (continued). "Another small molecule SBI‐0640756 (SBI‐756), as a first‐in‐class inhibitor targeting EIF4G1 and disrupting the EIF4F complex, showed inhibitory effects on tumour growth." (PMID 33523588, 2021). "Our group recently reports that the expressional level of EIF4G1 is much higher in NSCLC cell lines and primary tumor tissues, than their normal controls." (PMID 28903455, 2017). "Another study confirms that knock-down of EIF4E or EIF4G1 prevents NSCLC cell migration and epithelial-to-mesenchymal transition (EMT), which represent essential steps for tumor metastasis." (PMID 28903455, 2017). "Here we first time report that EIF4G1 expression is greatly up-regulated in NSCLC cell lines and tumor tissues when compared to those normal controls." (PMID 27003362, 2016). "Functional assays indicate that EIF4G1 is involved in NSCLC cell survival/proliferation, and multiple malignant behaviors for tumor development." (PMID 27003362, 2016). "However, after adjusting for other risk factors (age, tumor stage, chemosensitivity and cytoreduction), the eIF4G1 expression level was not an independent prognostic factor for OS (hazard ratio, 0.985; 95% CI, 0.524 to 1.85; P = 0.96) and PFS (hazard ratio, 1.235; 95% CI, 0.64 to 2.37; P = 0.53)." (PMID 27668427, 2016). "Eukaryotic translation initiation factor 4 gamma 1(EIF4G1) is related to tumorigenesis and tumor progression." (PMID 27003362, 2016). "Moreover, eIF4G1 was previously shown to be significantly overexpressed in human inflammatory-type breast cancer, which exhibits a similar pathological phenotype to that of the 4T1 tumor, in which 40–50% of cells involved in the overall tumor mass are immune cells." (PMID 25993439, 2015). "For instance, over-expression of EIF4G1 has been found in inflammatory breast cancer (IBC) and promotes the formation of IBC tumor emboli by enhancing translation of IRES-containing p120 mRNA, which facilitated tumor cell survival." (PMID 20398343, 2010). "Furthermore, our results indicate that PF-309 inhibits key signaling pathways involved in CRC progression, including the mTOR, p70 S6K, EIF4G1, NF-κB, IKB-α, c-Myc, WNT3A, and β-catenin pathways, underscoring its broad spectrum of anti-tumor effects." (PMID 41459112, 2026). "In the current study, we further demonstrate that EIF4G1 has much higher expressional levels in NSCLC tumour tissues than paired adjacent or normal lung tissues by using tissue microarrays, regardless of EIF4G1 IHC labelling scores for each case." (PMID 33539648, 2021). "We first detected the expression of EIF4G1 in several NSCLC cell lines and collected tumor tissues." (PMID 27003362, 2016). "eIF4G1 is also overexpressed in inflammatory breast cancer, where it reprograms the translational machinery to increase translation of mRNA with internal ribosome entry sites (IRES) that promote cell survival and tumor emboli." (PMID 23102376, 2012). "EIF4G1 may be used as a useful molecular marker for NPC and an indicator for tumor progression and prognosis." (PMID 20398343, 2010). "Among the eIF proteins, we found that eIF4G1 was one of the most differentially expressed proteins lung metastases, when comparing the control and SB-431542 treatment groups, and its expression was exclusively localized to the tumor and not the surrounding lung tissue." (PMID 25993439, 2015). "Here we report that the levels of EIF4G1 expression are much higher in NSCLC cell lines and tumor tissues than those in the normal lung cells and adjacent normal tissues from the same patients." (PMID 27003362, 2016).
transmission disease (1 paper, 2019). "At the moment, four genes are known, clearly implicated in autosomal dominant Parkinson’s disease—the SNCA/PARK1–PARK4 gene, the LRRK2/PARK8 gene, the VPS35/PARK17 gene, and the EIF4G1/PARK18 gene; instead, PARK-1 and DJ-1 genes are involved in the autosomal recessive transmission disease." (PMID 31817546, 2019).
EIF4G1 also shares sentences with these, for which no sentence is quoted: hepatocellular carcinoma (5 papers); lymphoma (5); Calicivirus infection (3); glioblastoma (3); kidney stone (3); poliovirus infection (3); Zika Virus Infection (3); acute myeloid leukemia (2); Cerebral ischemia (2); cholangiocarcinoma (2); chronic lymphocytic leukaemia (2); diabetes (2); diffuse large B-cell lymphoma (2); enteroviral infection (2); Esophageal carcinoma (2); multiple myeloma (2); neurological disorders (2); osteosarcoma (2); pancreatic ductal adenocarcinoma (2); retinoblastoma (2); Rotavirus infection (2); sarcoma (2); skin cutaneous melanoma (2); type 2 diabetes (2); acute lymphoblastic leukemia (1); acute promyelocytic leukemia (1); adenocarcinoma (1); adrenal cancer (1); astrocytomas (1); Atrophy (1).
A further 40 diseases each share a sentence with EIF4G1 in 1 paper.